APLNR (apelin receptor)
Diseases named in the same sentence as APLNR in open-access papers (continued):
Sharing a sentence is not in itself a finding about the gene and the disease.
tumor (70 papers, 2012 to 2025). "In cancer development, apelin is implicated in activating the apelin receptor, APJ, which is overexpressed in tumor tissues." (PMID 38255203, 2024). "Although the precise mechanism of action has to be determined, we have shown all cell types present in GBM that have been implicated in tumour progression, express the apelin receptor." (PMID 38803685, 2024). "APLN/APLNR signaling has been demonstrated to associate with neovascularization, tumor vessel density, microvascular proliferation, and tumor growth in other types of tumors." (PMID 36959862, 2023). "While APLN showed only very weak association with tumour histological grade (TCGA cohort), APLNR/mRNA protein expression correlate significantly with ccRCC aggressiveness." (PMID 30783205, 2019). "In support of our mRNA findings, we observe by immunohistology that APLNR expression in the vasculature and tumour cells associates inversely with tumour aggressiveness (pT-stage and grade as surrogates)." (PMID 30783205, 2019). "In both subcutaneous ectopic and intracranial orthotopic xenograft models, inhibition of APLNR was associated with a significant reduction in tumour volume together with a reduction in vascularization, proliferation and an increase in apoptosis." (PMID 29053791, 2017). "In keeping with a role for apelin in the stem cell maintenance, we found that differentiated GSCs were associated with a decrease in APLNR expression compared to tumourspheres and reduced tumour-initiating ability." (PMID 29053791, 2017). "Hence, the notoriously low invasiveness that is generally observed with the U87MG cell line seemed to be increased upon loss-of tumor-derived apelin/APLNR signaling." (PMID 32545380, 2020). "Interestingly, vascular APLNR expression was positively associated with microvessel density, which itself correlates negatively to tumour aggressiveness (ISUP grade)." (PMID 30783205, 2019). "Our study contributes to this field by discovering novel APLNR antagonists and exploring the role of APLNR antagonists in modulating tumor vascular normalization and exploring its potential as an antitumor therapeutic agent." (PMID 41316451, 2025). "As research progresses, APLNR inhibitors have shown remarkable efficacy in pathological neovascular diseases and have been validated as a novel target for anti-tumor therapeutics." (PMID 41316451, 2025). "Our study employed the drug repurposing strategies discovered that the existing approved drug candesartan act as a novel APLNR antagonist and exhibited significant potential in promoting tumor vascular normalization." (PMID 41316451, 2025). "Given that, we employed the drug repurposing approach to discover drug entities with the function of modulating tumor vascular normalization by antagonizing APLNR." (PMID 41316451, 2025). "The APLN/APLNR system is involved in tumor angiogenesis, and APLNR antagonists have a significant effect on pathological neovascularization diseases." (PMID 41316451, 2025). "The anti-tumor effect of apelin-dm was comparable to the effect of the apelin receptor antagonist ML221." (PMID 39962271, 2025). "The Apelin receptor (APLNR), a class A G-protein coupled receptor, plays a crucial role during cardiovascular development and tumor angiogenesis." (PMID 40691309, 2025). "Apelin, an emerging systemic factor, assumes a pivotal role in tumor advancement, angiogenesis, and the establishment of a premetastatic niche in potential metastatic organs through its intricate interaction with apelin receptor." (PMID 39962271, 2025). "For this reason, inhibitors of the apelin/APLNR axis are currently being investigated as potential antitumoral agents with the ultimate goal of avoiding tumor vascularization." (PMID 41515992, 2025). "This study aimed to discover novel APLNR inhibitors, examine their role in tumor vascular normalization, and assess their combinatorial potential with existing anti-cancer therapies." (PMID 41316451, 2025).
tumor (continued). "The data confirm the presence of the apelin receptor as a tractable drug target that is common across the key cell populations driving tumour growth and maintenance, offering a potential novel therapeutic approach for patients with GBM." (PMID 38803685, 2024). "The Apelin/APLNR system is increased in some cancers, is involved in tumor microenvironment reshaping and modulates tumor immune response." (PMID 37684649, 2023). "In various cancers, Apelin expression increases, and the Apelin/APLNR axis play an essential role in tumor development by enhancing angiogenesis, metastasis, cell proliferation, and cancer stem cell development and drug resistance." (PMID 35174205, 2022). "For APLNR, 11 datasets exhibited elevated level, whereas 6 datasets displayed reduced level in tumor tissues." (PMID 36193059, 2022). "Using real-time PCR, APJ was found to be expressed in all tumor cell lines tested, albeit at low levels, but similar to those obtained in human umbilical vein endothelial cells (HUVEC), described to endogenously express apelin receptor (Figure A5a)." (PMID 36142542, 2022). "APLN/APLNR was reported to be involved in the regulation of tumor growth, cancer cell migration, neoangiogenesis, and apoptosis in different types of cancers." (PMID 36193059, 2022). "Apelin receptor (APLNR) expression was negatively related to PD-L1 expression by tumor cells in a subset of patients with ccRCC and the expression of APLNR has been recognized as an independent prognostic factor for survival of patients with ccRCC." (PMID 33686949, 2021). "APLNR and its ligand apelin are involved in promoting tumor angiogenesis via multiple autocrine and paracrine mechanisms." (PMID 35052372, 2021). "In that paper, the authors showed that APLNR-positive tumor cells started to disseminate when Apelin levels were reduced both in in vitro and in vivo, and that data from patient samples were consistent with this in humans." (PMID 34234274, 2021). "These experiments highlighted intratumoral ECs as one major source for APLN in neoplasia and suggested that autocrine APLN/APLNR signaling in ECs co-controls tumor angiogenesis." (PMID 34359800, 2021). "In summary, recent research on APLN/APLNR signaling in tumor pathology indicates that pharmacological modulation of the APLN/APLNR pathway can act as anti-angiogenic and anti-invasive treatment." (PMID 34359800, 2021). "Comparing expression data of GBM patients from the TCGA database, we found that genes co-regulated with APLNR fell into Gene-Clusters primarily correlating with an anti-tumor immune response." (PMID 34359800, 2021). "Invading GBM cells can express high levels of APLNR, and this elevated expression correlates with increased expression of genes involved in tumor cell invasion like MMP2 or BAI1/3." (PMID 34359800, 2021). "Upon binding to the apelin receptor APJ, this adipokine is involved in several physiological functions as angiogenesis, heart contractility, energy metabolism and tumor progression." (PMID 33972642, 2021). "The APLN/APLNR pathway is upregulated in malignant cells in many tumor types, as well as in tumor endothelial cells, and elevated Apelin levels are associated with disease progression and poor clinical outcome." (PMID 31690961, 2020). "By functional analysis of apelin in orthotopic GBM mouse models, we found that apelin/APLNR signaling is required for in vivo tumor angiogenesis." (PMID 32545380, 2020). "To better understand the roles of the top candidate genes in response to anti-VEGF inhibition, we decided to focus on APLN and APLNR, both of which were found to be upregulated in the stroma from the resistant tumors compared to sensitive tumor stroma." (PMID 32002127, 2020). "In the TCGA ccRCC cohort, APLNR mRNA expression levels were negatively correlated with histological grade (Pearson’s r = −0.22, p = 5.2e−07) and pT-stage of the tumour (Pearson’s r = −0.23, p = 2.7e−07)." (PMID 30783205, 2019).
tumor (continued). "APLNR is expressed in tumour vasculature and tumour cells at different levels, and these expression levels associate with tumour aggressiveness in opposing directions." (PMID 30783205, 2019). "APLNR expression was negatively correlated with PD-L1 expression by tumour cells in a subset of patients with ccRCC." (PMID 30783205, 2019). "Immunohistochemical analysis of APLNR protein expression has provided important information concerning which compartments of the tumour tissue express the receptor." (PMID 30783205, 2019). "It would be interesting to compare the expression of APLNR/APLN in paired samples from primary tumours and metastases." (PMID 30783205, 2019). "So they used ML221, an apelin receptor antagonist, to treat tumor-bearing mice, and observed that ML221 treatment was effective on decreasing tumor growth." (PMID 30984306, 2019). "To verify that ML221 targets APLNR on tumor cells, we silenced APLNR in HepG2 and PLC5 cells using siRNAs." (PMID 31410213, 2019). "Increasing aggressiveness is accompanied with higher APLNR expression in tumour cells and lower expression in vessels." (PMID 30783205, 2019). "At the mRNA level, we have demonstrated that APLNR expression is decreased in higher grade, higher stage and metastatic ccRCC tumours with independent prognostic significance for overall and cancer-specific survival." (PMID 30783205, 2019). "Microvessel density was negatively correlated with ISUP grade of the tumour (Pearson’s r = 0.22, p = 0.0003) and was positively correlated with intensity of vascular APLNR expression (Pearson’s r = 0.21, p = 0.0002)." (PMID 30783205, 2019). "While the Apelin receptor has been detected in both tumor and endothelial cells, we find that its expression was considerably higher in tumor‐associated endothelial cells (Fig EV2C)." (PMID 31267692, 2019). "Our analysis of microvessel density, which is associated both with aggressiveness of the tumour (ISUP grade) and vascular expression of APLNR, once more supports this point." (PMID 30783205, 2019). "Marked reduction in the mRNA expression of apelin and the apelin receptor were evident in hearts of tumor-bearing mice." (PMID 31851697, 2019). "Functionally, selective competitive antagonists of apelin receptor were shown to be safe and effective in reducing tumour expansion and lengthening the survival of intracranially xenografted mice." (PMID 29053791, 2017). "Together, these in vivo data indicate that pharmacological inhibition of APLNR efficiently and safely reduces tumour growth in xenografted female animals." (PMID 29053791, 2017). "We next tested the effect of pharmacological inhibition of APLNR with MM54 in an ectopic xenograft tumour model." (PMID 29053791, 2017). "Here, we provide evidence that both in vitro and in vivo inhibition of APLNR results in a significant reduction in tumour growth." (PMID 29053791, 2017). "Apelin is known to signal through the G-protein coupled receptor APLNR (also known as APJ), which is reported to be highly expressed throughout the brain and act as paracrine and autocrine factor that supports embryonic and tumour angiogenesis." (PMID 29053791, 2017). "Furthermore, this study provided a comprehensive evaluation of candesartan’s effects on both in vitro and in vivo models, highlighting its potential as a novel anti-tumor agent by targeting APLNR." (PMID 41316451, 2025). "Aberrant expression of APLNR may influence the tumor microenvironment and diminish the efficacy of cancer immunotherapies." (PMID 41515956, 2025). "In cancerous tissues, the loss of crypts was associated with a modified expression pattern of apelin, apelin receptor, and Furin, suggesting that these molecules may play roles in tumor progression and possibly in the tumor microenvironment." (PMID 39962271, 2025). "APLN/APLNR signal is upregulated in several types of malignant T-cells and tumor ECs." (PMID 36959862, 2023).
tumor (continued). "Several reports indicate that apelin is often over-expressed in tumors, and therefore it has been suggested that the apelin–apelin receptor (APJ) system may induce tumor progression." (PMID 36776217, 2023). "Apelin expression is increased in various kinds of cancer and the apelin/APLNR axis plays a key role in the development of tumours through enhancing angiogenesis, metastasis, cell proliferation and also through the development of cancer stem cells and drug resistance." (PMID 36553076, 2022). "In addition, we discuss how manipulation of APLN/APLNR signaling in GBM leads to the normalization of tumor vessels and thereby supports chemotherapy, reduces edema, and improves anti-tumorigenic immune reactions." (PMID 34359800, 2021). "By immunohistological analysis of APLNR in tumor-bearing mice, we could confirm such a neuronal expression pattern." (PMID 34359800, 2021). "The apelin receptor (Apj) is highly expressed in the sprouting endothelial cells but minimally expressed in the cells of other tissues in homeostasis and has been demonstrated as a potential target for tumor therapy." (PMID 32358530, 2020). "The clinical outcome of targeting APLN/APLNR pathway for cancer therapy depends on the tumor type." (PMID 31690961, 2020). "Interestingly, targeting vascular APLNR by conditional ablation of APLNR-positive tumor vessels led to a significant reduction of tumor growth." (PMID 32545380, 2020). "On the basis of previous research and our current results, we speculate that CXCRs may interact with APLN/APLNR axis to regulate the immune state of the tumor microenvironment in ccRCC." (PMID 33324682, 2020). "Little is known about the role of APLNR/APLN axis during oncogenesis/tumour growth." (PMID 30783205, 2019). "However, it is unclear why increasing aggressiveness of the tumour leads to decreased levels of APLNR expression." (PMID 30783205, 2019). "Moreover, we observed a positive correlation between apelin and apelin receptor tumour tissue level with ρ = 0.279 and p = 0.039." (PMID 31547096, 2019). "Although the Apelin/Apelin receptor pathway is downregulated in adulthood, it is frequently reactivated and upregulated in tumors, including in endothelial cells within the tumor microenvironment." (PMID 31267692, 2019). "Furthermore, inhibition of the apelin receptor resulted in a reduction in tumor size, vascularization, proliferation, and an increase in apoptosis." (PMID 29875677, 2018). "In these conditions, the number of progressing tumours was modestly reduced in APLNR shRNA." (PMID 29053791, 2017). "In addition to their role in regulating tumor progression, APLNR is mainly involved in the neuroactive ligand-receptor interaction and vascular development, while ANXA2 mainly participates in the modulation of depressive behavior and signal transduction pathways." (PMID 33123575, 2020). "This slight decrease in tumour formation suggested that APLNR contributes to tumour expansion, although compensatory mechanisms may take place due to alternate signalling or an incomplete knockout of APLNR gene." (PMID 29053791, 2017). "We have shown that blood vessels in GBM tissue express the apelin receptor, expanding on previous findings showing expression of apelin peptide in GBM tumour blood vessels." (PMID 38803685, 2024). "Both APLN and the Apelin receptor (APLNR) are upregulated in GBM cells and control tumor cell invasiveness." (PMID 34359800, 2021). "Using adult APLN-creER and APLNR-creER transgenic mouse models, it was confirmed that APLN/APLNR expression is low in adult physiology but it is upregulated in ECs during tumor angiogenesis." (PMID 34359800, 2021). "Moreover, animals implanted with APLNR knocked down cells (shAPLNR GSC#9) were associated with a reduction in tumour burden compared to control groups, indicating that APLNR may be intrinsically important for tumour development." (PMID 29053791, 2017).
tumor (continued). "Specifically, we found a low positive correlation between APLN and CYR61 (r = 0.16), a stronger correlation between APLNR and CYR61 (r = 0.68), a low correlation between APLNR and RIC8A (r = 0.20), and a moderate correlation between APLNR and TUBA1A (r = 0.58) in tumor patients." (PMID 39962271, 2025). "Other studies, however, suggest that there is no direct relationship between the apelin/APLNR axis and the degree of tumor malignancy; rather, it depends on the cell type that generates the tumor." (PMID 41515992, 2025). "Apelin was identified as a central regulator of endothelium-dependent tumour initiation and maintenance in GBM cells with stem-like properties, and the apelin receptor antagonist, MM54, was used to successfully reduce tumour expansion and lengthen survival in a GBM xenograft mouse model." (PMID 38803685, 2024). "Endothelial cells were detected throughout the tumor stroma, and particularly showed strong attribution to apelin receptor (APLN), a gene involved in maintaining pro-angiogenic states among endothelial cells, possibly indicating active tumor neovascularization." (PMID 36906603, 2023). "Recently, APLN receptor (APLNR) was considered to be an essential gene for tumor immunotherapy, which can modulate the function of CD8+T cells, but the immunological effects of the APLN/APLNR axis in ccRCC remain unknown." (PMID 33324682, 2020). "In addition, protamine inhibits tumor angiogenesis via attaching to VEGFR, PDGFR and apelin receptor." (PMID 33382703, 2020). "In a renal cell carcinoma study, APLNR expression in a subset of patients was found to be negatively correlated with tumor PD-L1 expression." (PMID 31690961, 2020). "Moreover, cells that also expressed mRNA for the APELA receptor, APLNR, were also detectable by RNA-ISH in these discrete “nests” of tumor cells." (PMID 30917521, 2019). "A negative correlation was evident between APLNR expression and PD-L1 expression by tumour cells: for cytoplasmic APLNR expression: Pearson’s r = −0.16, p < 0.001, for vascular expression: Pearson’s r = −0.19, p < 0.001." (PMID 30783205, 2019). "MM54 did not induce alterations to these parameters, reflecting no obvious detrimental action of APLNR antagonism in tumour-bearing animals." (PMID 29053791, 2017). "Interestingly, in our study we were able to detect significant levels of negative correlation between APLNR expression in different tumour tissue compartments and PD-L1 expression by tumour cells in a subset of patients with ccRCC." (PMID 30783205, 2019). "The expression of the apelin receptor and its endogenous ligands has not been mapped in the diverse stem cell populations in GBM that drive tumour initiation, renewal, and resistance to current therapies." (PMID 38803685, 2024). "Accordingly, pharmacological blockade of apelin, but not the reduction of APLNR expression in GSCs, may also contribute to the reduction of tumour volume observed in this study in vivo, by blocking angiogenesis and depriving tumour cells of the nutrients they require to survive." (PMID 29053791, 2017).